CGAS (cyclic GMP-AMP synthase)
Diseases named in the same sentence as CGAS in open-access papers (continued):
Sharing a sentence is not in itself a finding about the gene and the disease.
tumor (continued). "To determine whether the increased cGAS-STING-IFN signaling in Ogt knockout cells provides an activated signal for single epitope-specific CD8+ T cell priming by antigen-presenting cells (APCs), we added the supernatant from B16-OVA tumor cells into the co-culture system of BMDCs and OT-I cells." (PMID 38168435, 2024). "In addition, studies have shown that the cGAS-STING signaling pathway is closely related to a variety of diseases such as tumors, autoimmune diseases, cardiovascular diseases, metabolic diseases, and neurodegenerative diseases, and has great potential to enhance tumor immunity and improve diseases." (PMID 38693578, 2024). "Interestingly, among TET family members, tumor suppressor TET2 expression was most positively correlated with cGAS expression and no negative correlation between tumor cGAS expression and DNA methyltransferases (DNMTs) was observed in HCC from TCGA and ICGC datasets." (PMID 38177099, 2024). "However, cGAS-STING scores were not related to tumor size (P = 0.38)." (PMID 38167507, 2024). "Finally, we propose that the PTEN protein is required for the proper functioning of the cGAS-STING pathway and that STING agonists may not be effective in GBM tumours with PTEN loss." (PMID 38214828, 2024). "Importantly, activation of cGAS-STING pathway by STINGa in Herceptin-resistant BC could reverse IFN signaling activity, which promotes anti-tumor immune response and have a synergistic anti-tumor effect with DS-8201 in vitro and in vivo." (PMID 38993569, 2024). "However, while controls responded sensitively to 5-FU, cGAS-knockdown tumours did not." (PMID 39080411, 2024). "Therefore, more investigations are needed on how specific bacteria or their products can stimulate the cGAS-STING pathway and enhance the anti-tumor immune response, which may promote the development of novel therapeutic strategies or interventions for CRC treatment." (PMID 37781354, 2023). "has shown that succinate produced by F. nucleatum could inhibit the cGAS-IFNβ pathway, leading to reduced levels of chemokines CCL5 and CXCL10 in the tumor, thereby limiting the migration of CD8+ T cells to TME and suppressing the anti-tumor response of CD8+ T cells." (PMID 38023192, 2023). "However, tumor cell-intrinsic expression of cGAS, but not STING, was significantly reduced in pMMR/MSS CRC from patients who experienced recurrence within five years after curative resection, regardless of whether they had received adjuvant chemotherapy." (PMID 37345163, 2023). "Therefore, the enhanced activation of cGAS/STING pathway was expected to promote dendritic cell (DC) maturation, natural killer cell (NK) infiltration, cytotoxic T lymphocyte (CTL) activation, and reduce immunosuppressive cells in tumour microenvironment (TME)." (PMID 38264691, 2023). "However, it is important to note that cGAS/STING activity alone is inadequate to induce EMT or account for invasive behavior; moreover, at least in some models, the activation of NF-κB has anti-tumor effects even when it occurs alongside aneuploidy (in nude mice with hepatic metastasis)." (PMID 38139802, 2023). "This indicated that the peptide loaded on the wild‐type, but not the cGAS silencing, tumor cell surface enhanced the activity of effector/memory CD8+ T cells in vitro, suggesting that cGAS silencing in the target tumor cells might hinder the further activation of CD8+ T cells." (PMID 37986544, 2023). "However, whether radiotherapy induces cGAS-STING-mediated anti-tumor effects or not is related to the applied radiation dose." (PMID 35889509, 2022). "Furthermore, RocA dramatically activated the cGAS (cyclic GMP-AMP synthase)-STING (stimulator of interferon genes) signaling pathway, and the inhibition/depletion of STING ablated the up-regulation of CCL5 and CXCL10, NK cell infiltration, and tumor regression induced by RocA." (PMID 35002511, 2022).
tumor (continued). "In addition, aside from being produced directly through the cGAS-STING pathway, IFN-β production by tumor cells might occur indirectly through the existing gap junctions, where cGAMP transfers from DCs to the tumor cells, thus inducing the transcription of IFN-β genes." (PMID 35292881, 2022). "In contrast, using agonists to activate the cGAS-STING signaling pathway, thereby antagonizing the inhibitory signals of this pathway and reversing the immunosuppressive state, may be a more feasible approach, which is expected to break the resistance bottleneck of these tumor immunotherapies." (PMID 36353640, 2022). "Furthermore, PARP inhibitors may increase tumor immunogenicity via immunogenic cell death and expansion of the neoantigen repertoire, cGAS-STING pathway activation, upregulation of PD-L1 expression, and immunomodulation of the tumor microenvironment to reflect a TH1 immune response." (PMID 35954359, 2022). "Moreover, the metastasis of tumor cells may be driven by non-autonomous cGAS/STING pathway-related mechanisms." (PMID 35046953, 2021). "Nonetheless, these collective data suggest overall that tumor STING regulates the cell-intrinsic response to DNA damage through mechanisms independent of its canonical cGAS–STING cytosolic DNA-sensing pathway and that activation of this pathway may increase the efficacy of DNA-damaging therapies." (PMID 34884568, 2021). "Given that tumor cells frequently undergo necrosis, DNA damage and nuclear rupture—all of which would expose the cytoplasm to an abundance of genomic DNA—the question remains: why are tumor cells not critically inhibited and destroyed by cGAS-STING-mediated immunosurveillance?" (PMID 32774773, 2020). "Importantly, we also observed that cancer cell cGAS deletion significantly decreased expression of both CXCL10 and IFN-β in co-cultured HUVECs, providing direct evidence that ablation of 2′3′-cGAMP export from tumor cells suppresses STING signaling in endothelial cells." (PMID 33013881, 2020). "Thus, expression of the cGAS-STING and DNA-damage marker histone γH2AX in tumor cells could be considered as independent prognostic factors to predict therapy response and clinical outcome, and could be superior to that of traditional markers like immunogenic cell death and T cells number." (PMID 32411126, 2020). "Since we previously found that Mn was critically involved in innate immune sensing of cytosolic dsDNA to activate the cGAS-STING pathway, which is important for exerting antitumor immune responses, we hypothesized that Mn would also play roles in innate immune responses against tumor cells." (PMID 32839553, 2020). "Additionally, only a subset of patients across malignancies can generate a natural anti-tumour T-cell response due to cGAS-STING activation, whilst others will show no such spontaneous immunity, underscoring the complexity of the role of this pathway in tumorigenesis." (PMID 33081170, 2020). "However, such compounds will also block innate immune surveillance and, therefore, while such small molecule inhibitors have the potential to block CIN tumors from becoming metastatic, cGAS/STING inhibition might come at the price of local immune suppression and thus impaired tumor clearance." (PMID 31658669, 2019). "However, activation of the cGAS-STING pathway does not always confer anti-tumor effects." (PMID 31658669, 2019). "By linking NONO depletion to cGAS/STING pathway activation, we provide a new perspective on how tumor cells can be targeted to enhance anti-tumor immunity." (PMID 40943463, 2025). "The HPV16-related OPSCC tumor model showed upregulation of cGAS and STING, without corresponding cytokine induction, suggesting potential for future studies using STING agonists or antagonists to modulate tumor response." (PMID 41401057, 2025).
tumor (continued). "Thus, our findings align with existing literature on the pro-immunogenic role of cGAS/STING–IFN signaling and provide mechanistic insight into how PRMT1 loss may enhance anti-tumor immunity without contradicting the broader understanding of inflammation’s dual roles in cancer." (PMID 40858547, 2025). "This indicates that the contribution of cGAS-STING signaling to the BRCA1/2–PARPi SL is not tumor cell-autonomous (i.e., it relies on non-tumor cell lineages) and is best explained by cGAS-STING signaling activating a T-cell-mediated immune response." (PMID 40730818, 2025). "Collectively, our findings reveal a pathway that links noncanonical cGAS/STING signaling to gasdermin E–mediated pyroptosis, thereby offering valuable insights for tumor therapy." (PMID 40663398, 2025). "cGAS and STING expression was assessed in tumor cells, independent of expression in the stromal area, using the IHC score (H-score) as described in Methods section." (PMID 40451897, 2025). "Unlike these tumor-intrinsic adaptations, we demonstrate that OASL impairs ICD by directly binding cGAS and suppressing cGAS-STING signaling pathway, thereby inhibiting dendritic cell maturation and CD8+T-cell infiltration." (PMID 41271618, 2025). "Without cGAS or DRP1 aggregation, mitoROS accumulation and ferroptosis increase, inhibiting tumor growth." (PMID 40754534, 2025). "SAMHD1 inhibits cGAS-STING pathway–mediated innate and adaptive immunity, and the absence of SAMHD1 reduces tumor-free survival." (PMID 40236649, 2025). "Conversely, when TREX1 is not induced, the cGAS-STING pathway is activated and recruits BATF3-dependent dendritic cells that activate anti-cancer CD8+ T cells to mediate systemic tumor immunity." (PMID 39759116, 2025). "This discovery suggests that the absence of JMJD8 alleviates the inhibition of the cGAS-STING pathway, thereby activating antitumor immunity and restricting tumor proliferation." (PMID 40761260, 2025). "Taken together, these data suggest that HO-1 inhibited the function of both cGAS and STING in tumor cells under RT independent of its enzymatic activity." (PMID 39621310, 2024). "On one side, this work demonstrates that cancer cell-intrinsic expression of cGAS, but not STING, determines tumor vascular normalization and anti-tumor immune response in a host STING-dependent manner." (PMID 38177099, 2024). "The utilization of Mn2+ as an agonist can directly stimulate the inherent cGAS–STING cascade in NK cells, without relying on tumor cells, and enhances the responsiveness of NK cells." (PMID 39206412, 2024). "Since cGAMP is known to be transmitted between cells, cGAMP produced by cGAS in cancer cells, which are frequently lack of intrinsic STING, is prone to be secreted to tumor microenvironment, leading to host STING activation." (PMID 38177099, 2024). "Chromatin immunoprecipitation (ChIP) assays showed that H101 treatment (MOI of 100) induced significant H3K4 trimethylation (me3) enrichment at the cGAS promoter (P1–P2) in SW620 and LOVO tumor cells compared to the nontreated control." (PMID 38782895, 2024). "The DNA accumulated in apoptotic tumor cells and non-neoplastic cells within the tumor microenvironment (TME) is believed to act as the initiator for the cGAS pathway." (PMID 39420203, 2024). "Tumor LRRC8C expression negatively correlated with vascular invasion when cGAS was highly expressed, whereas no obvious correlation was shown in low cGAS expression group." (PMID 38177099, 2024). "Our findings validate that Mn2+ can enhance the responsiveness of NK cells by activating NK cell–intrinsic cGAS and STING, independent of the existence of tumor cells." (PMID 39206412, 2024). "For the LID + US group, knocking out cGAS from MC38 tumor cells did not compromise the IFNβ secretion from BMDC, indicating cGAS in MC38 was not required to mediate the APC activation." (PMID 37391428, 2023).
tumor (continued). "As tumoral cGAMP can directly induce IFNβ secretion from BMDC without requiring functional cGAS in BMDC, these results indicate that tumor DNA, rather than tumoral cGAMP, mainly mediated the activation effect." (PMID 37391428, 2023). "Radiotherapy leads to dsDNA accumulation in cancer cells when Trex1 is not activated type I IFNs are activated through the cGAS/STING pathway, downstream recruitment of DCs, and activation of CD + 8 T cells or anti-PD-1 antibodies to initiate tumor rejection." (PMID 37667279, 2023). "The IHC analyses revealed that 76.1% of all pMMR CRCs were cGAS-negative expressions, and 70.8% of all pMMR CRCs were STING-negative expressions in tumor cells." (PMID 37345163, 2023). "Moreover, cGAS-STING, which is attracting considerable attention for its ability to promote antitumor immune responses, may fundamentally be able to address many of the barriers limiting the success of cancer immunotherapy strategies, including the immunosuppressive tumor microenvironment." (PMID 37627155, 2023). "In contrast, in dMMR CRC, cGAS−/STING− CRC cases were observed in only 20% of all dMMR CRCs, and 52.5% of dMMR CRC lacked cGAS expression, while 40.0% lacked STING expression in tumor cells." (PMID 37345163, 2023). "CIN instigates IL-6-STAT3 mediated signaling via the cGAS-STING pathway and the noncanonical NF-kB pathway, thus promoting tumor cell growth and metastasis." (PMID 37920470, 2023). "Intriguingly, decreased methylation of cGAS and STING promoters was observed in most tumors, indicating that tumor cells do not normally grow by silencing the cGAS-STING pathway." (PMID 37122745, 2023). "While the absence of cGAS or STING does not directly induce carcinogenesis, it is clear that the action of innate immunity precedes the priming of tumor antigen-specific CD8+ T cells." (PMID 38139802, 2023). "Previously published TCGA-based studies investigated STING expression in head and neck tumors at the transcriptomic level but did not discriminate between the impact of intrinsic tumor cell-specific STING signaling and cGAS–STING activation in immune cells." (PMID 37444620, 2023). "In consistent, we found that the protein expressions of STING, cGAS, p-IRF3, p-TBK1, and PD-L1 were increased in the irradiated tumor although the protein expressions of IRF3 and TBK1 were not increased." (PMID 35847556, 2022). "In the absence of cGAS or STING, SASP and immune cell infiltration are defective, and the clearance of RasV12-expressing cells is impaired leading to tumor development." (PMID 36591232, 2022). "(2014) analyzed a subset of mouse mutants with defective innate immunity-sensing signaling molecules and found that disruption of cGAS–STING, but not other receptors, reduced tumor CD8+ T cell infiltration and compromised host tumor control." (PMID 35325182, 2022). "A point mutant of TEAD converts NF2 into a potent suppressor of cGAS/STING signaling, strongly inhibiting cGAS/STING-mediated cell-autonomous and nonautonomous tumor immunity and suppressing nucleic acid recognition." (PMID 36497453, 2022). "Altogether, Nectin-1 expression correlated with T-VEC induced tumor cell regression in vitro and in vivo, while respective expression of HVEM, STING, and cGAS did not predict response." (PMID 34205379, 2021). "We also observed upregulation of CGAS, STING (TMEM173) mRNA and downstream inflammatory response pathway effectors induced by CIN, including noncanonical NF-κB targets in patient tumor cells ranked according to the average GEP2 gene expression signature." (PMID 34518527, 2021). "Unlike other metal ions, Mn2+ can also activate cGAS-STING pathway and further promote tumor immunity, finally achieving antitumor effect from two aspects." (PMID 34656118, 2021). "DNA that is not degraded by tumor-intrinsic TREX1 can stimulate the cGAS-STING pathway to generate an IFN-response and drive immune cell recruitment to facilitate tumor regression." (PMID 33868310, 2021).
tumor (continued). "We show that the presence of platelets, myeloid cell–derived FXa, and thrombin reduces the uptake of tumor cell–derived nucleic acids, while lack of myeloid cell FX expression or FXa-PAR2 signaling conversely increases cGAS-STING-IFN-I induction in vitro and in vivo." (PMID 40694429, 2025). "However, clinical trials with cGAS‐STING pathway agonists have faced setbacks thanks to their short biological half‐life, lack of tumor specificity, and potential to promote tumor immune evasion." (PMID 40548883, 2025). "We hypothesized that, unlike cGAS or STING, other nucleic acid sensing pattern recognition receptors (PRR) might be essential for BRCAm tumor cells." (PMID 40730818, 2025). "Notably, the 5-FU mediated effects on tumor cells were not exerted directly, but instead activated the cGAS/STING1 pathway and promoted anti-tumor immunity." (PMID 40105196, 2025). "Notably, despite the persistent activation of the cGAS-STING pathway within tumor cells, it not only fails to promote the immune system's ability to eliminate these cells but also facilitates tumor migration." (PMID 38512518, 2024). "In addition to immune cell or tumor cell-intrinsic cGAS-STING activation, cGAS-STING pathway allows the cross-talk between tumor cells and surrounding non-tumor cells (or host cells) to regulate anti-tumor immunity." (PMID 38177099, 2024). "Additionally, we found that either the absence of cGAS or STING significantly suppressed immune activation and anti‐tumor effect induced by the combination treatment." (PMID 39412086, 2024). "MnP was nontoxic to normal cells and was able to activate the cGAS-STING pathway and promote type I interferon production, thus inducing tumor cell ICD, M1 polarization, DC maturation, antigen presentation, and T cell-mediated tumor cell killing." (PMID 38994034, 2024). "Furthermore, we observed a significant positive correlation between tumor cell-intrinsic expression of STING, but not cGAS, and the number of CD8+ TILs in GCs." (PMID 39242811, 2024). "Interestingly, it has been found that competitive uptake of methionine by tumor cells activated the methyltransferase SUV39H1 and promoted the methylation of cGAS, thus promoting the chromatin tethering of cGAS without activation." (PMID 38515746, 2024). "Thus, in future study, a pinpoint cGAS-STING expression state should be better characterized in both immune cells and non-immune cells including tumor cells as well as stromal cell resident in bone marrow environment of AML patients." (PMID 38510490, 2024). "However, the functional interaction between chronic cGAS–STING activation as a consequence of CIN and the tumour landscape has not been closely examined." (PMID 36876871, 2023). "Interestingly, we found that tumor cell-intrinsic expression of STING, but not cGAS, was decreased in the advanced stages of pMMR CRC, and the percentages of cases lacking cGAS-STING expression in tumor cells increased in stages II and IV of pMMR CRC." (PMID 37345163, 2023). "MN can activate the cGAS-STING pathway and upregulate the downstream noncanonical nuclear factor-kappa B pathway, thereby promoting enhanced fitness and metastasis in chromosomally unstable tumor cells." (PMID 37569723, 2023). "Moreover, HFD and cGAS KO decreased IR‐promoted tumor regression, but not substantially additively, raising the role of HFD in cGAS‐dampened tumor growth." (PMID 36950761, 2023). "Activation of the cGAS-STING pathway not only induces CTLs-mediated cancer cell death by upregulating MHC-I expression on the surface of cancer cells, but also activates NK cells to kill tumor cells, especially those with reduced or absent MHC-I expression." (PMID 36353640, 2022). "The cGAS-STING pathway was not activated in MB49 in the presence of dsDNA, but responded to direct stimulus of cGAMP producing CXCL10 and expressing IFN-β, which suggests that cGAS is not active in this tumor cell line." (PMID 34341449, 2021).